IQCN (IQ motif containing N)
Description:
Essential for spermiogenesis and fertilization. May be required for manchette assembly in elongating spermatids (By similarity).
Synonyms: KIAA1683; SPGF78
Tractability: No criterion of Open Targets' tractability assessment is met for any kind of drug.
Gene: Protein-coding gene on chromosome 19 (18,257,098 to 18,274,500, reverse strand). Ensembl gene ENSG00000130518.
Subcellular location (Human Protein Atlas): Acrosome; Equatorial segment
Gene Ontology:
Molecular function: protein binding
Biological process: spermatid development
Cellular component: mitochondrion; nucleus
Genetic constraint (gnomAD): Loss-of-function variants: 46 observed, 66.39 expected, observed/expected ratio (o/e) 0.69, 90% interval 0.55 to 0.89. The upper end of that interval is the gene's LOEUF score, 0.89, which puts it in group 3 of 6, group 1 being the genes least tolerant of losing a copy. Missense variants: 1,753 observed, 1,907.7 expected, observed/expected ratio (o/e) 0.92, 90% interval 0.88 to 0.96. Synonymous variants: 733 observed, 797.94 expected, observed/expected ratio (o/e) 0.92, 90% interval 0.86 to 0.98.
Homologues: Orthologues: chimpanzee IQCN (96% identical), macaque IQCN (74% identical), dog IQCN (57% identical), mouse Iqcn (47% identical), rat Iqcn (46% identical). Paralogues in human: IQCE (9% identical).
Diseases named in the same sentence as IQCN in open-access papers:
IQCN is named in the same sentence as 6 diseases in open-access papers, as found by Europe PMC text mining. Sharing a sentence is not in itself a finding about the gene and the disease. The quoted sentences say what the papers report.
male infertility (4 papers, 2022 to 2026). The inability of the male to effect fertilization of an ovum after a specified period of unprotected intercourse. "Although there are no available studies on the association between IQCN and male infertility, a few studies have elucidated the involvement of IQCG in spermatogenesis; spermiogenesis specifically." (PMID 35173218, 2022). "Research on the epidemiological links between IQ motif family genes (IQUB, IQCN, IQCH) and male infertility, while establishing initial genotype-phenotype correlations, is constrained by significant limitations that affect the generalizability and depth of conclusions for each gene." (PMID 41602861, 2026).
asthenozoospermia (1 paper, 2026). "Pathogenic variants such as the homozygous IQUB c.942T > G mutation are linked to asthenozoospermia, while loss-of-function IQCN mutations cause total fertilization failure." (PMID 41602861, 2026). "Specific loss-of-function mutations are strongly linked to distinct clinical phenotypes: IQUB variants to asthenozoospermia, IQCN mutations to total fertilization failure, and IQCH deficiency to azoospermia." (PMID 41602861, 2026). "Within the subset of cases with a genetic etiology, mutations in specific IQ motif genes have been established as monogenic causes for distinct phenotypes: IQUB (c.942T > G) with asthenozoospermia, IQCN (c.1061_1062delAT) with total fertilization failure, and IQCH variants with azoospermia." (PMID 41602861, 2026).
cancer (2 papers, 2019 to 2024). A tumor composed of atypical neoplastic, often pleomorphic cells that invade other tissues. "Interestingly, IQCN was found to be downregulated; however, no reports currently link this gene to cancer." (PMID 39409923, 2024). "Interestingly, the downregulated expression of IQCN was observed in both cell lines; however, to date, no reports link this gene to cancer." (PMID 39409923, 2024).
IQCN also shares sentences with these, for which no sentence is quoted: acute leukemia (1 paper); Azoospermia (1); hypothyroidism (1).